TTR (transthyretin)
Diseases named in the same sentence as TTR in open-access papers (continued):
Sharing a sentence is not in itself a finding about the gene and the disease.
dementia (23 papers, 2011 to 2026). Loss of intellectual abilities interfering with an individual's social and occupational functions. "In ATTR, a previous study reported a case of a 72-year-old male with the rare Tyr69His TTR gene variant, dementia, and ataxia." (PMID 36198883, 2023). "We report the neuropathologic findings from a brain autopsy of a 72-year-old man with the rare Tyr69His (Y69H) TTR gene variant, dementia and ataxia." (PMID 26156087, 2015). "TTR has been previously shown to have associations with senile systemic amyloidosis and plasma cell dyscrasias providing some evidence of a direct linkage to the immune response and potentially to the dementia-related effects of SVDs." (PMID 29632138, 2018). "In contrast, severe meningovascular amyloidosis is associated with certain TTR gene mutations, including Leu12Pro, Asp18Gly, Ala25Thr, Val30Gly, Val30Met, Thr49Pro, Leu58Arg, Phe64Ser, Tyr69His and Tyr114Cys, and can lead to dementia and ataxia." (PMID 26156087, 2015). "To provide novel insights into the potential neuropathologic substrates of dementia and ataxia in this disorder, we present the postmortem neuropathologic findings from a patient with dementia, ataxia and meningovascular amyloidosis associated with the rare Tyr69His (Y69H) substitution in TTR." (PMID 26156087, 2015). "Indeed, patients treated with warfarin with a lower TTR, are at higher risk of dementia." (PMID 34043846, 2021). "We first downloaded the expression values of TTR from the human aging, dementia, and TBI dataset in Allen Brain Atlas." (PMID 34983929, 2022). "The plasma TTR level at the point when they converted to dementia was significantly lower than that at baseline (328.6 ± 66.5 vs. 381.9 ± 77.6 ug/ml, p < 0.001)." (PMID 31822765, 2019). "In MCI converters (n = 62), the plasma TTR levels were checked again for 51 patients (82.2%) at the point when they converted to dementia." (PMID 31822765, 2019). "The present study demonstrates that MCI patients have higher plasma TTR levels compared with cognitively healthy controls and that higher plasma TTR levels are associated with MCI-to-dementia conversion." (PMID 31822765, 2019). "During the MCI stage, the TTR levels keep increasing and the patients with higher TTR levels tend to convert to AD, but after conversion to the dementia stage, the TTR levels drop and lower TTR levels reflect rapid cognitive decline." (PMID 31822765, 2019). "To gain potential insights into the pathogenesis of these deficits in meningovascular amyloidosis, we report our postmortem neuropathologic findings from a patient with dementia, ataxia and the rare Tyr69His (Y69H) TTR substitution." (PMID 26156087, 2015). "The clinical features of defects in TTR include seizures, stroke-like episodes, dementia and psychomotor deterioration." (PMID 24225037, 2013). "Plasma TTR levels were lower in Dementia-AD, especially in women." (PMID 41820479, 2026). "Even though Aβ is the superstar of dementia, other proteins are also involved in neurodegenerative diseases, such as cystatin, transthyretin, and the British and Danish types of amyloid these proteins accumulated in the brain and vessels in a way that they can also affect brain function." (PMID 38164365, 2024). "To exclude the possibility of biological differences of TTR expression from aging and dementia samples from Allen Brain Atlas, we repeated this analysis, examining TTR percentile rank expression in the GTEx dataset, focusing only on the 12 brain regions that were profiled." (PMID 34983929, 2022). "Furthermore, our results showed decreased plasma TTR levels at the point when MCI patients converted to dementia." (PMID 31822765, 2019). "Decreased CSF levels of TTR occur in severe dementia and AD." (PMID 25705176, 2015).
dementia (continued). "The aim of the present study was to investigate the thiol-conjugated TTR isoforms as support for the differential diagnosis of AD and related dementias by applying the method on clinically well-characterized samples collected under uniform and highly controlled conditions." (PMID 24678637, 2014). "Variables such as medical history of aspiration pneumonia and dementia, use of dentures, NT-proBNP, TLC, BUN, CRP, albumin, transthyretin, MMSE, handgrip strength, prehospital MSAS and MSAS, MPT, and prehospital BI and BI, were entered into a multivariate model." (PMID 27898735, 2016). "Patients with TTR meningovascular amyloidosis often show dementia, however the neuropathologic features of dementia in these cases have not been elucidated." (PMID 26156087, 2015).
autonomic neuropathy (22 papers, 2013 to 2025). An inherited or acquired peripheral neuropathy affecting the autonomic nervous system. "In the present report, we describe a novel amyloidogenic TTR mutation, p.Gly87Arg, associated with vitreous amyloidosis and autonomic neuropathy of the digestive tract in a Bangladeshi patient." (PMID 28802308, 2017). "We report a case of vitreous opacity and severe autonomic neuropathy of the digestive tract associated with a novel TTR amyloidogenic variant, p.Gly87Arg." (PMID 28802308, 2017). "We describe a case of a Bangladeshi patient presenting with ATTR amyloidosis with vitreous amyloid deposition and autonomic neuropathy of the digestive tract as initial clinical manifestations, and associated with a novel amyloidogenic TTR mutation, Gly67Arg (p.Gly87Arg)." (PMID 28802308, 2017). "To date, more than one hundred amyloidogenic TTR mutations have been identified leading to a variety of clinical manifestations ranging from peripheral and autonomic neuropathy, to cardiomyopathy, ophthalmopathy and vitreous opacities and carpal tunnel syndrome, among others." (PMID 27589730, 2016). "One of the most common TTR mutations, V30M-TTR, is associated with peripheral and autonomic neuropathy at the early stages of the disease (FAP), a hereditary autosomal dominant lethal disease that may affect individuals from their twenties." (PMID 27589730, 2016). "This form is primarily hereditary, resulting from point mutations in transthyretin (TTR) protein, leading to peripheral and autonomic neuropathy." (PMID 39597824, 2024). "Patients present with diverse symptoms related to sensory, motor, and autonomic neuropathy, as well as gastrointestinal, ocular, cardiac, renal and orthopedic symptoms, resulting from the deposition of transthyretin amyloid fibrils in multiple organs." (PMID 37828588, 2023). "FAP, or transthyretin (TTR) amyloid polyneuropathy, is a progressive sensorimotor and autonomic neuropathy of adult onset, which is characterized by systemic accumulation of amyloid fibrils constituted of aberrant TTR protein." (PMID 33917266, 2021). "Gastrointestinal symptoms, as a manifestation of autonomic neuropathy, are recognized from an early stage of TTR-FAP and include nausea, early satiety, recurrent vomiting, watery diarrhea, severe constipation, and/or alternating diarrhea and constipation." (PMID 23425518, 2013). "In ATTR-CM, the native tetrameric form of TTR, produced mainly in the liver, pathologically dissociates to form amyloid fibrils that deposit in the myocardium, nerves, and soft tissues, and peripheral and/or autonomic neuropathy." (PMID 38068302, 2023). "TTR‐FAP and dPNP both present with motor, sensory, and autonomic neuropathy." (PMID 29568686, 2018).
Stroke (22 papers, 2013 to 2025). Sudden impairment of blood flow to a part of the brain due to occlusion or rupture of an artery to the brain. "In conclusion, lower serum transthyretin levels are associated with more severe ICAS lesions in patients with stroke." (PMID 36212641, 2022). "There is evidence that decreased serum transthyretin levels are associated with poor prognoses in stroke patients, even when stroke severity and vascular risk factors are considered." (PMID 36212641, 2022). "TTR has been implicated in stroke and ischaemia, in which it is overproduced by the choroid plexus to control neuronal cell death, oedema, and inflammation." (PMID 34215285, 2021). "Some immediate effects on lesion size 24 hours after stroke onset were observed in TTR deficient mice heterozygous for heat shock transcription factor 1 (HSF1)." (PMID 31479465, 2019). "Transthyretin was independently associated with functional outcome at discharge and one-year mortality in stroke patients, after adjusting for potential confounders." (PMID 28636639, 2017). "The association between the reported mean TTR and major bleeding and stroke/systemic embolism was analyzed by random-effects meta-regression with and without adjustment for relevant clinical cohort characteristics." (PMID 29155884, 2017). "Serum level of TTR at admission was a predictor of functional outcome after ischemic stroke and was also associated with one-year mortality in stroke survivals." (PMID 28636639, 2017). "In univariable meta-regression, increasing mean TTR was significantly associated with a decreased rate of both major bleeding and stroke/systemic embolism." (PMID 29155884, 2017). "For example, it is necessary to confirm changes in the expression levels of thyroid hormone or AF-related stroke diagnostic biomarkers, such as TTR by obtaining samples at several time points, such as before stroke occurrence in patients with AF, at occurrence, after occurrence, and after recovery." (PMID 38886511, 2024). "A prolonged TTR can be expected to be associated with a reduced risk of stroke and as a consequence might result in a beneficial stroke prevention therapy compared to DOACs." (PMID 32847578, 2020). "Our findings indicated that RBP4 and TTR are related to hypertriglyceridemia and insulin resistance; therefore, these markers may involve the risk of heart disease and stroke." (PMID 29747616, 2018). "The associations of RBP4 and TTR with hypertriglyceridemia and insulin resistance may have important implications for the risk of heart disease and stroke." (PMID 29747616, 2018). "The decrease of TTR levels associated with more severe stroke outcome detected in our research can be other component of acute phase response elicited in the course of critical illnesses as infection, trauma, surgery, myocardial infarction as well as ischemic stroke." (PMID 28636639, 2017). "Several possible pathophysiologic mechanisms underlying the association between low TTR level and unfavorable stroke outcome could be considered." (PMID 28636639, 2017). "An interesting hypothesis which could explain the association of TTR concentration and stroke severity is based on the role of this protein in the thyroid hormones transport." (PMID 28636639, 2017). "The difference in lesion size and outcome between TTR deficient mouse strains might be explained by reduced or suppressed levels of HSF1 resulting in a compromised heat shock response during the first hours after stroke onset." (PMID 31479465, 2019). "In patients with stroke, TTR has been described as a positive prognostic indicator of clinical outcome." (PMID 33919289, 2021). "After stroke, TTR immunopositive cells have been detected in the infarct core 24 h after permanent occlusion of the middle cerebral artery with no expression of ttr in the postischemic brain." (PMID 31479465, 2019).
Stroke (continued). "During the discussion, we will elaborate on possible functions of TTR in the brain and discuss results regarding the expression of TTR after stroke." (PMID 31479465, 2019). "According to previous studies, motor neurons synthetize and secrete TTR, playing a role as a neuroprotective factor in AD and stroke." (PMID 30577465, 2018). "Similarly, a lower transthyretin concentration at admission in stroke patients is an independent predictor of long-term mortality after mechanical thrombectomy." (PMID 39478501, 2024). "The unknown role of TTR in recovery processes after stroke prompted us to study its expression in the post-ischemic brain." (PMID 31479465, 2019). "The unknown role of the carrier protein transthyretin (TTR) in mechanisms of functional recovery in the postischemic brain prompted us to study its expression following experimental stroke." (PMID 31479465, 2019). "Therefore, the link–low TTR level, poor nutritional status, unfavorable stroke outcome, is quite conceivable." (PMID 28636639, 2017). "Recent study has shown that changes in TTR concentration could be related to infections developed in the course of stroke." (PMID 28636639, 2017). "Having identified megalin as the receptor involved in the transduction of TTR neuroprotection in hippocampal neuronal cell culture, we investigated whether megalin was involved and/or affected in a mice stroke model– pMCAO." (PMID 27518433, 2016). "Hence, the upregulation of TTR in CSF and/or megalin neuronal upregulation should be addressed as potential preventive therapies for stroke." (PMID 27518433, 2016). "Therefore, testing thyroid hormones, in addition to this AF-related biomarker, such as TTR, may be helpful in distinguishing stroke subtypes related to AF in patients with stroke." (PMID 38886511, 2024). "Alterations of nutritional status have been described in stroke patients in terms of body composition (i.e., fat-free mass or calf circumference), energy expenditure, and laboratory tests (for instance, vitamin status and plasma proteins such as transferrin and transthyretin)." (PMID 36771390, 2023). "These two interrelated proteins, megalin and TTR, could be further explored as possible endogenous neuroprotective targets, which can be potentiated in a novel preventive/prognostic strategy in different pathologies, certainly in stroke." (PMID 27518433, 2016). "Benzoin, a TCM used for stroke treatment, exerts its effects through targets such as phosphodiesterase 4D (PDE4D), ACE, and transthyretin (TTR), as suggested by network pharmacology and molecular docking studies." (PMID 40606624, 2025). "When we analyzed the changes in the proteome of patients 90 days after stroke versus 45 days, only 2 proteins, K2C78 and TTR, were significantly overexpressed in the HT group." (PMID 38732018, 2024). "After stroke, TTR immunopositive cells were found in the ischemic territory 24 hours after permanent middle cerebral artery occlusion (MCAO) and migration of TTR from CSF has been suggested." (PMID 31479465, 2019). "Alternatively, a decrease in TTR and RBP expression levels was observed in patients with stroke compared to the healthy controls, and this might have occurred due to the stroke-induced inflammatory response." (PMID 38886511, 2024). "Also, the result of the different studies showed the TTR serum level was the predicting factor for the clinical outcome, and mortality after surgery, in TBI and stroke patient." (PMID 33224232, 2020). "Independent of its role as a transport protein, TTR has been studied as neuroprotective molecule in brain pathologies such as stroke." (PMID 31479465, 2019). "Although FTL was more expressed than AHSG, TTR, and FGG using gene expression data for normal human tissues, it remains debatable whether iron itself and iron accumulation were beneficial or harmful after experimental stroke." (PMID 34168538, 2021).
Stroke (continued). "Although TTR is absent from brain parenchyma after stroke, it is neuroprotective in vitro models of ischemia, and we cannot exclude that CP derived TTR may provide similar effects in vivo." (PMID 31479465, 2019). "A1AG1, CRP, and LBP were upregulated, while TTR, ApoC2, and RBP4 were downregulated in patients with stroke and AF, compared to patients with stroke without AF." (PMID 38886511, 2024). "In contrast, the levels of transthyretin (TTR), apolipoprotein C-II (ApoC2), and retinol-binding protein 4 (RBP4) were lower in patients with stroke and AF compared to those without AF." (PMID 38886511, 2024). "Interestingly, in patients with stroke and AF, proteins involved in the inflammatory response (CRP, LBP, and A1AG1) were significantly increased compared to those without AF, and TTR and RBP were significantly decreased." (PMID 38886511, 2024).
Obesity (21 papers, 2014 to 2025). Accumulation of substantial excess body fat. "Increased levels of TTR have been associated with glucose intolerance, obesity, and decreased pancreatic β-cell percentage in T2DM." (PMID 37686344, 2023). "In summary, the results suggest a role of TTR in cardiac fibrosis development associated with obesity and the beneficial effects of treatment with mitochondrial antioxidants." (PMID 35897655, 2022). "Recently, a human study found that circulatory RBP4 and TTR is associated with glucose intolerance and obesity, and T2DM and RBP4 is associated with insulin resistance." (PMID 29747616, 2018). "Among the observed changes it was remarkable that weight loss in obese children ameliorated the obesity induced decrease in Apo-A1 by increasing the expression of two of its isoforms (#2201; #7201), as well as increasing transthyretin (#5103)." (PMID 24949022, 2014). "TTR further contributes to immune balance by promoting myeloid cell differentiation and modulating chemokine signaling, helping to regulate innate immunity and limit chronic inflammation, a hallmark of obesity." (PMID 40981199, 2025). "Positioned at the metabolism and cardiovascular health crossroads, TTR plays a pivotal role in maintaining systemic balance, and in our study, it exhibited the strongest downregulation among the identified adiposome-associated proteins in obesity." (PMID 40981199, 2025). "Future deployment of single-cell approaches will allow us to define in detail the localization, expression and role of TTR in each cardiac cell types, increasing our knowledge about the molecular mechanisms involved in the cardiac alterations associated with obesity." (PMID 35897655, 2022). "Overall, these associations, along with the marked reduction in TTR in obese adiposomes, may signal the loss of a key regulator of metabolic, vascular, and immune homeostasis, positioning TTR as a promising biomarker and therapeutic target in obesity." (PMID 40981199, 2025). "These diverse functions highlight TTR as a molecular safeguard across systems commonly disrupted in obesity; yet the extent to which TTR exerts similar functions in adipose or vascular compartments remains to be fully elucidated." (PMID 40981199, 2025). "On the other hand, TTR levels have been demonstrated to be increased in the mouse model of obesity, type 2 diabetes, and in pregnant women with gestational diabetes." (PMID 34199897, 2021). "Chronic icv infusion of TTR in Otsuka Long-Evans Tokushima Fatty rats reversed hyperphagia and obesity and reduced DMH NPY levels." (PMID 27053000, 2016). "Together, these results not only establish a novel function of brain TTR, but also provide a potential target for the prevention and treatment of obesity and its comorbidities." (PMID 27053000, 2016). "Key predictive proteins such as C9, TTR, CRP, and S100A9 are not only differentially abundant in obesity but also implicated in the pathogenesis of endothelial dysfunction, systemic inflammation, and insulin resistance, further validating their mechanistic relevance." (PMID 40981199, 2025). "Indeed, the expression of hepatic TTR is increased by a high‐fat diet and obesity and, at the same time promotes insulin resistance." (PMID 39039431, 2024). "Finally, the utility of our lead DB-lipidoid was demonstrated through hepatic delivery of Cas9 mRNA/sgRNA for gene editing of transthyretin (TTR) and human fibroblast growth factor 21 (FGF21)-encoded mRNA for the treatment of obesity and fatty liver." (PMID 38409275, 2024). "Overall, these studies examining factors that might modulate DMH NPY demonstrated a novel anorectic action of central TTR in the control of energy balance, providing a potential novel target for obesity treatment." (PMID 27512691, 2016). "Overall, these results demonstrate a previously unknown anorectic action of central TTR in the control of energy balance, providing a potential novel target for treating obesity and its comorbidities." (PMID 27053000, 2016).